RIPK3 (receptor interacting serine/threonine kinase 3)
Description:
Serine/threonine-protein kinase that activates necroptosis and apoptosis, two parallel forms of cell death. Necroptosis, a programmed cell death process in response to death-inducing TNF family members, is triggered by RIPK3 following activation by ZBP1. Activated RIPK3 forms a necrosis-inducing complex and mediates phosphorylation of MLKL, promoting MLKL localization to the plasma membrane and execution of programmed necrosis characterized by calcium influx and plasma membrane damage. In addition to TNF-induced necroptosis, necroptosis can also take place in the nucleus in response to orthomyxoviruses infection: following ZBP1 activation, which senses double-stranded Z-RNA structures, nuclear RIPK3 catalyzes phosphorylation and activation of MLKL, promoting disruption of the nuclear envelope and leakage of cellular DNA into the cytosol (By similarity). Also regulates apoptosis: apoptosis depends on RIPK1, FADD and CASP8, and is independent of MLKL and RIPK3 kinase activity (By similarity). Phosphorylates RIPK1: RIPK1 and RIPK3 undergo reciprocal auto- and trans-phosphorylation. In some cell types, also able to restrict viral replication by promoting cell death-independent responses (By similarity). In response to Zika virus infection in neurons, promotes a cell death-independent pathway that restricts viral replication: together with ZBP1, promotes a death-independent transcriptional program that modifies the cellular metabolism via up-regulation expression of the enzyme ACOD1/IRG1 and production of the metabolite itaconate (By similarity). Itaconate inhibits the activity of succinate dehydrogenase, generating a metabolic state in neurons that suppresses replication of viral genomes (By similarity). RIPK3 binds to and enhances the activity of three metabolic enzymes: GLUL, GLUD1, and PYGL. These metabolic enzymes may eventually stimulate the tricarboxylic acid cycle and oxidative phosphorylation, which could result in enhanced ROS production. (Microbial infection) In case of herpes simplex virus 1/HHV-1 infection, forms heteromeric amyloid structures with HHV-1 protein RIR1/ICP6 which may inhibit RIPK3-mediated necroptosis, thereby preventing host cell death pathway and allowing viral evasion.
Synonyms: RIP3
Tractability: Small molecule: a structure with a bound ligand is known; a high-quality ligand is known; it belongs to a druggable protein family. PROTAC: UniProt records ubiquitination sites on it; ubiquitination databases record sites on it; its protein half-life has been measured; a small molecule that binds it is known.
Target class: Protein Kinase; TKL protein kinase group; Kinase; Enzyme
Gene: Protein-coding gene on chromosome 14 (24,336,025 to 24,340,022, reverse strand). Ensembl gene ENSG00000129465.
Subcellular location: Cytoplasm, cytosol; Nucleus
Pathways (Reactome):
Immune System: IKK complex recruitment mediated by RIP1; RIP-mediated NFkB activation via ZBP1; TICAM1, RIP1-mediated IKK complex recruitment; TLR3-mediated TICAM1-dependent programmed cell death; TRIF-mediated programmed cell death
Disease: Microbial modulation of RIPK1-mediated regulated necrosis; SARS-CoV-1 activates/modulates innate immune responses; SARS-CoV-1-mediated effects on programmed cell death
Programmed Cell Death: RIPK1-mediated regulated necrosis; Regulation of necroptotic cell death
Transport of small molecules: TRP channels
Gene Ontology:
Molecular function: identical protein binding; protein binding; protein kinase activity; protein serine kinase activity; protein serine/threonine kinase activity; protein serine/threonine kinase binding; protein-containing complex binding; transcription coactivator activity; ATP binding
Biological process: activation of protein kinase activity; amyloid fibril formation; intracellular signal transduction; necroptotic process; necroptotic signaling pathway; positive regulation of necroptotic process; ripoptosome assembly involved in necroptotic process; apoptotic signaling pathway; cellular response to hydrogen peroxide; defense response to virus; execution phase of necroptosis; lymph node development; programmed necrotic cell death; regulation of activated T cell proliferation; regulation of activation-induced cell death of T cells; regulation of adaptive immune response; regulation of apoptotic process; regulation of CD8-positive, alpha-beta cytotoxic T cell extravasation; regulation of T cell mediated cytotoxicity; regulation of type II interferon production; signal transduction; spleen development; T cell differentiation in thymus; T cell homeostasis; thymus development; and 3 more
Cellular component: cytosol; nucleus; protein-containing complex; ripoptosome; cytoplasm
Genetic constraint (gnomAD): Loss-of-function variants: 51 observed, 52.89 expected, observed/expected ratio (o/e) 0.96, 90% interval 0.77 to 1.22. The upper end of that interval is the gene's LOEUF score, 1.22, which puts it in group 5 of 6, group 1 being the genes least tolerant of losing a copy. Missense variants: 654 observed, 683.67 expected, observed/expected ratio (o/e) 0.96, 90% interval 0.9 to 1.02. Synonymous variants: 246 observed, 274.12 expected, observed/expected ratio (o/e) 0.9, 90% interval 0.81 to 1.
Homologues: Orthologues: chimpanzee RIPK3 (99% identical), pig RIPK3 (60% identical), mouse Ripk3 (57% identical), dog RIPK3 (55% identical), guinea pig RIPK3 (54% identical), rat Ripk3 (54% identical), tropical clawed frog ripk3l.2 (25% identical), zebrafish ripk3 (21% identical). Paralogues in human: MAP3K20 (22% identical), MAP3K9 (20% identical), MAP3K10 (19% identical), LRRK2 (18% identical), RIPK2 (18% identical), MAP3K21 (17% identical), MAP3K11 (17% identical), TESK1 (17% identical), MAP3K12 (16% identical), RIPK1 (16% identical), MAP3K13 (16% identical), LIMK2 (15% identical), and 11 more.
Diseases named in the same sentence as RIPK3 in open-access papers:
RIPK3 is named in the same sentence as 357 diseases in open-access papers, as found by Europe PMC text mining. Sharing a sentence is not in itself a finding about the gene and the disease. The quoted sentences say what the papers report.
Sepsis (63 papers, 2014 to 2026). Sepsis is defined as life-threatening organ dysfunction caused by a dysregulated host response to infection. "In septic shock animal models, knockout of RIPK3, a key necroptosis-associated molecule, reduces circulating cell death markers and enhances AM survival, thereby mitigating sepsis-induced lung injury." (PMID 40817040, 2025). "Further pre-clinical studies showed that elevated RIPK3 concentrations are associated with sepsis and with sepsis-induced acute kidney injury (AKI)." (PMID 41009652, 2025). "Necroptosis contributes to sepsis-associated organ injury, and inhibiting key mediators like RIPK3 or RIPK1 alleviates systemic inflammation and organ damage in neonatal septic mice." (PMID 40832104, 2025). "Utilizing the in vivo CLP model, we found that the deficiency of Zbp1 and Ripk3 attenuated the severity of sepsis-induced ALI." (PMID 39465383, 2024). "Based on clinical trials, molecular mechanism studies have revealed that RIPK3, a marker of necroptosis, is positively associated with mortality and organ dysfunction in sepsis." (PMID 38161332, 2023). "In conclusion, plasma TRAIL level was inversely associated with sepsis severity and plasma level of RIPK3." (PMID 32492832, 2020). "Secondarily, we sought to build on our prior reports by determining the association of plasma RIPK3 levels with AKI and mortality in larger cohorts of sepsis and trauma patients and by determining patient characteristics associated with plasma RIPK3." (PMID 31253195, 2019). "The change in plasma RIPK3 from presentation to 48 h (ΔRIPK3) was associated with ARDS in sepsis (OR 1.30, 95% CI 1.03–1.63, per 1⁄2 standard deviation) and trauma (OR 1.79, 95% CI 1.33–2.40)." (PMID 31253195, 2019). "Our study expands on smaller reports that plasma RIPK3 is associated with AKI in sepsis and trauma patients." (PMID 31253195, 2019). "In agreement with the earlier report, we demonstrate that, even in our very severe model of CLP-induced sepsis, RIPK3 deficiency delayed mortality." (PMID 24996547, 2014). "Our data suggest that RIPK3 deficiency modestly protected from CLP-induced severe sepsis and altered the immune cell trafficking in an organ-specific manner attenuating organ injury." (PMID 24996547, 2014). "We first performed a seven-day survival study on WT and Ripk3-/- mice to confirm the effect of RIPK3 deficiency on a very severe model of CLP-induced polymicrobial sepsis." (PMID 24996547, 2014). "Considering that necrosis plays a major role in sepsis induced liver dysfunction, we next wanted to look at the effect of RIPK3 deficiency in sepsis-induced liver damage." (PMID 24996547, 2014). "If so, RIPK3 might be a beneficial therapeutic target in vascular diseases associated with high TNFα levels such as sepsis." (PMID 34153072, 2021). "The plasma level of TRAIL was inversely associated with RIPK3 in patients with sepsis." (PMID 32492832, 2020). "In animal model of septic shock, RIPK3 deficiency prevents the remarkable increase in circulating cell death markers and promotes survival, suggesting that targeting RIPK3 in sepsis might be beneficial." (PMID 29587748, 2018). "Interestingly, we note that RIPK3-deficient mice still show liver damage after CLP-induced sepsis in our model, though much less than WT mice." (PMID 24996547, 2014). "Whether RIPK3 plays a role in regulating the immunosuppressive phase of sepsis and altering the susceptibility to secondary infections needs to be further addressed in a milder CLP model and/or a second hit model with bacterial infection." (PMID 24996547, 2014). "However, it is unknown if RIPK3 deficiency has any impact on immune cell trafficking, which contributes to organ damage in sepsis." (PMID 24996547, 2014). "Flow cytometry analyses have demonstrated significantly increased intracellular RIPK3 expression in sepsis patients compared with healthy controls." (PMID 41009652, 2025).
Sepsis (continued). "RIPK-3 followed a similar pattern, showing increased levels in the sepsis group relative to SIRS in adults and to cardiac patients in children (p = 0.06)." (PMID 40722817, 2025). "RIPK-1 and RIPK-3, key mediators of the necroptosis pathway, were elevated in patients with sepsis across both age groups, with RIPK-1 reaching statistical significance (p < 0.001)." (PMID 40722817, 2025). "Our findings revealed a notable increase in the expression of ASC/caspase-8/RIPK3, key PANoptosis proteins, within T cells during sepsis." (PMID 40995563, 2025). "During sepsis, RIPK3-mediated necroptosis synergizes with GSDMD-induced pyroptosis, amplifying inflammatory signaling and exacerbating tissue damage." (PMID 40832104, 2025). "A study analyzing inpatients demonstrated that patients with severe sepsis and septic shock had markedly higher RIPK3 levels than those with general sepsis, and that RIPK3 levels were positively correlated with SOFA scores and PCT levels." (PMID 40817040, 2025). "According to earlier studies, RIPK3 protects mice against SIRS induced by TNF and sepsis caused by cecal ligation and puncture (CLP)." (PMID 38684668, 2024). "In summary, the inhibition of necroptosis mediated by the RIPK1/RIPK3/MLKL signaling pathway confers protective effects in the context of sepsis." (PMID 39544947, 2024). "Based on clinical trials, researchers have conducted molecular-level studies and found that the necroptosis marker RIPK3 is positively correlated with mortality and organ dysfunction in sepsis." (PMID 39544947, 2024). "Recent clinical trials have established necroptosis as a prognostic marker for mortality in sepsis patients, with RIPK3 levels being utilized as a biomarker for evaluating necroptotic processes." (PMID 39544947, 2024). "Clinical investigations have revealed that RIPK3 levels are markedly increased across all time points in patients with severe sepsis and septic shock compared to those with sepsis alone." (PMID 39544947, 2024). "To date, only two studies have tested RIPK3 levels in human blood, one in patients with septicaemia and the other in occupational Al-exposed workers." (PMID 38696138, 2024). "In kidney tubular epithelial cells, receptor-interacting protein kinase-3 (RIPK3) facilitated oxidative stress, and mitochondrial dysfunction implicating NOX4 and RIPK3 upregulation was necessary for elevated mitochondrial translocation of NOX4 in sepsis." (PMID 37284448, 2023). "Recent clinical trials have further demonstrated that necroptosis can serve as a predictor of mortality in sepsis patients, and RIPK3 levels can be utilized as a marker for assessing necroptosis." (PMID 38161332, 2023). "Given the complex array of potential signaling outcomes downstream of RIPK1 and RIPK3, the understanding of their role in sepsis remains incomplete and is actively evolving." (PMID 38274794, 2023). "In clinical sepsis, levels of RIPK3 were found to be significantly elevated at different time points." (PMID 38020710, 2023). "Similar positive feedback loops have been identified in sepsis, where RIPK3 and GSDMD signaling co-diffuse to amplify the inflammatory response and cytokine release in macrophages and endothelial cells." (PMID 38002346, 2023). "In this study, we also found that RIPK1 and RIPK3, which are key proteins involved in necroptosis, were significantly upregulated in patients with sepsis and septic shock." (PMID 37475188, 2023). "Clinical studies have revealed that RIPK3 levels in patients with severe sepsis and septic shock are significantly elevated compared to the sepsis group at all time points." (PMID 38161332, 2023). "Inhibition of RIPK3 attenuated cardiac ischemia‒reperfusion injury and sepsis by reducing mitochondrial dysfunction, and inhibition of the RIPK1-RIPK3 pathway reduced tumor cell metastasis by decreasing vascular endothelial permeability." (PMID 36828808, 2023).
Sepsis (continued). "A previous study reported that the expressions of RIPK3 in urine and plasma were increased in patients with sepsis." (PMID 36188562, 2022). "An emerging paradigm is that RIPK3 is a central mediator of lung tissue injury in murine models of acute lung injury (ALI), sepsis/systemic inflammatory associated organ injury, and chronic lung diseases." (PMID 36361505, 2022). "The therapeutic importance of RIPK kinase inhibition during sepsis is highlighted by the fact that RIPK3 deletion defends against sepsis models." (PMID 36059483, 2022). "A clinical study showed that in patients with sepsis, the expression of RIPK3 and MLKL connected with plasma HMGB1 levels, which were related to the severity and mortality of the condition." (PMID 36059483, 2022). "RIPK3 deletion in mice also provides protection from CLP-induced polymicrobial sepsis, as shown by increased survival and declined circulating DAMPs level, proinflammatory cytokines secretion, and the reduction of neutrophil infiltration." (PMID 36361505, 2022). "In view of the potential synergistic impact on sepsis-induced injuries, one study aimed to investigate the protective effect on double deletion of RIPK3 and GSDMD." (PMID 34824200, 2021). "Together with observation of mitochondrial depolarization in in vitro study, these findings have shed insights into RIPK3’s unique role in regulating mitochondrial function during sepsis-induced AKI." (PMID 34824200, 2021). "Serum RIPK3 in our study was assessed using an established commercial assay that has also been used to investigate necroptosis in sepsis." (PMID 32655398, 2020). "Recent studies examining the necroptosis regulators of RIPK1, RIPK3, and MLKL in patients with sepsis reported that their levels were associated with disease severity and/or mortality." (PMID 32492832, 2020). "After finding that RIPK3 was released by cultured lung endothelial cells undergoing red blood cell-induced necroptosis, we reported an association of plasma RIPK3 with RBC transfusions and mortality in 37 sepsis patients." (PMID 31253195, 2019). "It is highly plausible that programmed necrosis in the kidneys, as well as the lungs and other organs, results in elevated circulating RIPK3 levels in sepsis and trauma patients." (PMID 31253195, 2019). "In MESSI but not PETROS, this was true for presentation RIPK3 as well, possibly reflecting a greater delay from initial insult to ED presentation in sepsis patients, allowing more time for circulating RIPK3 to rise." (PMID 31253195, 2019). "As such, studies on Ripk3-deficient mice showed protective effects in models of TNF-induced SIRS and sepsis." (PMID 29606984, 2018). "Based on the collected data, the dynamic changes in these variables indicated that the plasma RIPK3 level was a reliable predictor for patient with sepsis." (PMID 29137405, 2017). "The plasma RIPK3 concentration is also helpful to monitor the development and prognosis of sepsis dynamically and accordingly, it has a great potential for therapeutic interventions in clinical practice." (PMID 29137405, 2017). "There were significant differences in the patients’ characteristics of APACHE II score, SOFA score, CRP level, PCT level, and RIPK3 level at 24 hours after sepsis diagnosed among three groups." (PMID 29137405, 2017). "Here, we demonstrate that IL-1β production during sepsis with uropathogenic E. coli is mediated by caspase-8, since caspase-8 and RIPK3 double knock out mice show substantially lower cytokine during sepsis and increased survival after injection of TNFα." (PMID 28428949, 2017). "Among the included sepsis patients, the primary infection sites, the concurrent chronic diseases, and the regulated proteins of necroptosis including RIPK3 and RIPK1 levels were prospectively collected." (PMID 29137405, 2017). "In our severe sepsis model, the mean survival time of Ripk3-/- mice was significantly extended to 68 hours compared to 41 hours for WT mice." (PMID 24996547, 2014).